RAC1 (Rac family small GTPase 1)
Diseases named in the same sentence as RAC1 in open-access papers (continued):
Sharing a sentence is not in itself a finding about the gene and the disease.
cancer (continued). "Interacting with TGFβ, Rac1 drives endothelial-to-mesenchymal transition (EndoMT) in cancer, in which endothelial cells lose their polarity and cohesiveness and acquire the morphology and migratory properties of fibroblasts." (PMID 37908840, 2023). "We also discuss the regulatory mechanisms of Rac1 in cell migration and highlight it as a potential target in cancer therapy." (PMID 37049739, 2023). "Its binding frequency with endogenous Rac1-GTP can be facilitated by rapid immunohistochemistry (R-IHC), so that Rac1 activation in cancer formalin-fixed paraffin-embedded (FFPE) tissues can be detected." (PMID 37049739, 2023). "RAC1 plays a major regulatory role in the basis of malignant tumor development, including tumor angiogenesis and invasion/metastasis." (PMID 37202394, 2023). "Rac1 activity is required for mature invadopodia formation and/or ECM degradation in some cancer cell lines, while Rac1 regulates invadopodia disassembly at the final stage in others." (PMID 37482421, 2023). "TRPV4 can affect tumor angiogenesis and inflammatory microenvironment, intervene in the cytoskeleton-related proteins including RhoA, CDC42, and Rac1, and promote cancer cells EMT." (PMID 37369706, 2023). "BPGAP1 recruits the RacGEF Vav1 under epidermal growth factor (EGF) stimulation and activates Rac1, leading to polarized cell motility, spreading, invadopodium formation, and cell extravasation and promotes cancer cell migration." (PMID 36598812, 2023). "Although the signaling pathway is not clear, CCDC85A promoted EMT, which activates Rac1/CDC42 in various cancer cells." (PMID 37534255, 2023). "IQGAP1 is a crucial regulator of cancer development by scaffolding and facilitating different oncogenic pathways, especially RAC1/CDC42, thus affecting proliferation, adhesion, migration, invasion, and metastasis." (PMID 37787041, 2023). "Among various types of cancer especially ESCC, the activity of Rho GTPase, in particular those of the family (including most studied members RhoA, Rac1, and Cdc42), have been strongly associated with tumor progression." (PMID 37752569, 2023). "As a proof of concept, we controlled Rac1-mediated signal transduction during lamellipodia formation, which plays a key role in metastasis and invasion of cancer cells." (PMID 36964170, 2023). "Third, given that high cholesterol levels are favourable for cancer growth, disruption of Rac1 activity and thus the colocalization of Rac1 in lipid rafts in cancer cells dampen their proliferation." (PMID 35698295, 2023). "RAC1 has been identified as playing important roles in cancer, particularly in the control of cell motility and metastasis, and has also been implicated in cancer cell proliferation." (PMID 37047360, 2023). "When we explored the role of genes in different tumors, we found that genes such as RAC1 and SHC1 were elevated in most cancers, suggesting their role as prognostic risk factors in most tumors." (PMID 36969076, 2023). "GTPases, such as RAC1, can activate EMT in multiple cancers, thus leading to a more invasive and drug resistant phenotype and we show that RAC1 expression is increased upon HDAC1 overexpression in PDAC cells." (PMID 37996815, 2023). "In this review, we firstly introduce the molecular structure and activity regulation of Rac1, and then summarize the role of Rac1 in cancer invasion/metastasis and other physiological processes." (PMID 37049739, 2023). "Rho-GTPases viz, Rac-1 and Cdc42 are the central regulators of cancer cell migration and invasion and thus metastasis in multiple cancer types." (PMID 37024613, 2023). "The results show that signaling by the Wnt/β-catenin pathway requires macropinocytosis, Rac1, and membrane trafficking in Xenopus embryos and cancer cells." (PMID 37902809, 2023). "Our results suggest that RAC1 prevents further cancer progression by blocking the transition from G0/G1 phase to S phase." (PMID 37202394, 2023).
cancer (continued). "In vitro experiments where Fascin-1 was either silenced by siRNA or shRNA or inhibited by a pharmacological inhibitor (compound G2) showed decreased cancer cell migration and impaired Cdc42 and Rac1 activity." (PMID 37511011, 2023). "Rac1 interacts with Akt1 to increase cancer cell stemness downstream of PODXL2 and also enhance cell migration through the Axl/Rac1/Akt1-mediated axis." (PMID 35456223, 2022). "Due to the important regulatory roles, RAC1 has been proposed as one of the etiological factors in multiple malignant tumors, including BC." (PMID 36443711, 2022). "Hypoxia increased the expression of Cdc42, Rac1, and RhoA in human cancer cells and microvascular endothelial cells." (PMID 35154449, 2022). "Though RAC1-MAPK axis has been demonstrated to be involved in the progression of several types of cancers, the efficient inhibition of RAC1-MAPK axis by MG53 was reported here for the first time." (PMID 35858925, 2022). "Previous findings have elucidated the functional cooperation between Hh signaling and Rac1 in cancer." (PMID 35154488, 2022). "RAC1 is an important intracellular signal transduction molecule that is closely related to the occurrence and development of malignant tumors and a tumor driver gene." (PMID 36404333, 2022). "To further evaluate the roles of RAC1 in different types of cancers, we investigated RAC1 expression by analyzing the RNA-seq data of multiple cancers in TCGA." (PMID 36552804, 2022). "In the new landscape of cancer genomics, activating point mutations in members of the RHO GTPases have been identified, in particular in RAC1, RHOA, and CDC42, which has suggested that RHO GTPases can indeed serve as oncogenes in certain cancer types." (PMID 35454871, 2022). "Further, it leads to an increase in the activation of Rac1 through Tiam1 expression that induces cancer cell migration toward metastasis." (PMID 35875090, 2022). "Lamellipodia-mediated migration is a key mode of metastasis in cancer, and Rac1 is a key regulator of lamellipodia and was found to be upregulated in our TCGA analysis." (PMID 35241781, 2022). "Among the common factors involved in cancer cell stemness, Rac1 stood out as the most upregulated protein in both T24T and UMUC3 cells." (PMID 36077697, 2022). "Rac1-Pak1 signaling, which is an important pathway for cancer cell migration, and tissue invasion is thus affected." (PMID 35327364, 2022). "Vav2 had been reported to upregulate cell motility by promoting the cycling between an inactive Rac1-GDP-bound state to an active Rac1-GTP-bound state in many cancer types." (PMID 35177591, 2022). "Taken together, these results demonstrated that metformin functions in the phosphorylation of DOCK1, resulting in the activation of RAC1, and consequently, deficiency of DOCK1 sensitizes cancer cells to metformin." (PMID 35217990, 2022). "Inhibition of Rac1 can inhibit tumor growth and restore the sensitivity of patients to cancer therapy." (PMID 35031595, 2022). "Pericellular hyaluronic acid (HA) secreted by CAMs can bind to CD44v3-Vav2 complex on OC cells to activate RhoGTPase (Rac1) pathway signaling, in turn, promoted the activation of cytoskeleton, finally facilitating cancer cells invasion." (PMID 36268019, 2022). "The GTPase Rac1, however, is not only of interest when it comes to pathologies of the cardiovascular system, but is also known to promote cancer chemoresistance, radioresistance, and immune evasion." (PMID 36293446, 2022). "In another study, mevalonate inhibition in cancer cells disrupts Rac1 prenylation to enhance recognition and cross‐presentation by conventional dendritic cells, providing a potential target for cancer immunotherapy." (PMID 35619540, 2022). "Deletion of RAC1 gene in cancer significantly reduced the tumor formation in the respective tissues, which indicated the critical involvement of RAC1 in tumor progression." (PMID 35858925, 2022).
cancer (continued). "The regulation of RAC1 is important for the manipulation of cancer and has attracted much attention in recent years." (PMID 35858925, 2022). "Rac1 and Erk activity are interconnected in many cancer types and are reportedly subject to reciprocal regulation." (PMID 36377725, 2022). "In short, Rac1 can participate in different signal pathways to mediate the occurrence and development of malignant tumors." (PMID 35682879, 2022). "SH3 domain‐binding protein 1 (SH3BP1) is a RhoGTPase‐activating protein that is important for the process of cell motility and cancer invasion through the regulation of the Rac1 pathway." (PMID 35352878, 2022). "PI3KCB can be activated by Cdc42 and Rac1, and inactivation of PIK3CB can significantly suppress tumor proliferation, metastasis, and invasion in in PTEN-deficient cancers." (PMID 35154449, 2022). "In contrast, NDV interacting with Rac1 GTPase in the lamellipodia of invasive cancer cells inactivates the cellular oncogenic signaling pathways." (PMID 35327364, 2022). "Grb2 not only activated Ras pathway signaling to regulate cancer cells growth, but also interacted with Vav2 to activate Rac1 pathway signaling." (PMID 36268019, 2022). "In agreement, loss of miR-204 results in BDNF/TRKB overexpression and activation of the Akt/mTOR/Rac1 signalling pathway, cancer cell migration and invasion in many cancers." (PMID 35158801, 2022). "As changes in cancer stemness are associated with the process of EMT, we next assessed the effect of RAC1 rescue in terms of the self-renewal/long term proliferation potential in RAB4A knockdown cells as assessed by serial replating sphere formation assay." (PMID 36307864, 2022). "Results from our group showed that stimulation of AT2R in metastatic cancer cells is associated with activation of PTP1B, reduction of pY14-CAV1 levels, Rab5/Rac1 activity, and inhibition of migration, invasion, and metastasis." (PMID 35740528, 2022). "Such endogenous TRAIL-dependent TRAIL-R2-mediated activation of the Rac1/PI3K/AKT pathway has been shown to promote migration, invasion and metastasis of KRAS-mutated cancer cells." (PMID 36158196, 2022). "Transfection with siMICAL1 in Caki-1 cells also led to a significant reduction in Rac1 activation (GTP form of Rac1), which has been proposed to have pro-migratory effects in most types of cancer cells." (PMID 36575439, 2022). "RAC1 is dysregulated in a variety of tumors including HCC, and the overexpression and hyperactivation of RAC1 are correlated with aggressive growth and other malignant characteristics of cancer cells." (PMID 35858925, 2022). "RAC1 activity is found to be elevated in many cancer types such as breast, gastric, and oral carcinomas." (PMID 36307864, 2022). "RAC1 has recently emerged as a critical regulator of tumor and a promising therapeutic target for cancer drug discovery." (PMID 35858925, 2022). "MVA suppression disrupts prenylation of the small GTPase Rac1 and induces cancer cell actin filament exposure, which can be recognized by CLEC9A specifically expressed on cDC1s and thus activating infiltrating T cells." (PMID 36003368, 2022). "Trans-endothelial migration of carcinoma cells was previously demonstrated to be Rac1 dependent with Rac1 knockdown or single copy deletion in vivo attenuating carcinoma cell trans-endothelial migration and hematogenous spread." (PMID 36444960, 2022). "Rho-family GTPases, including Ras-related C3 botulinum toxin substrate 1 (Rac1) and cell division control protein 42 (Cdc42), are important modulators of cancer-relevant cell functions and are viewed as promising therapeutic targets." (PMID 33413202, 2021). "In cancer biology, RNA helicase activity has been confirmed to be crucial for the promotion of cyclin E1 and Rac1 translation, whereas ATPase activity is important for P21 transcription." (PMID 33627125, 2021).
cancer (continued). "DOCK2 has the functions of activating small G proteins such as Rac1/2 and subsequently activates downstream pathways which involved in survival, proliferation and migration of cancer." (PMID 33259129, 2021). "For cancers with elevated activity of Rac1 and/or Rho/ROCK signaling, they are likely more sensitive to proinflammatory killing by NK cells via necroptosis." (PMID 34325694, 2021). "Recently, many studies have shown that RAC1 plays a critical role in multiple physiological and pathological processes, including cancer." (PMID 34307388, 2021). "The activation of RhoA, Rac1/2/3 and cdc42 small GTPases exerts an important molecular switching effect on cancer cell proliferation, migration, and invasion." (PMID 34345201, 2021). "RAC1 and Cdc42 GTPases are key signaling intermediates with important roles in cancer initiation and progression, and inhibitors of these proteins, including EHT1864, have shown promising preclinical efficacy." (PMID 33603169, 2021). "Regarding Rac1, the paradigm example we have focused on above, its overexpression has long been reported in many cancers, most frequently correlating with poor prognosis and therapeutic resistance." (PMID 34440759, 2021). "For instance, POTEE is upregulated in CRC, and it promotes cancer cell proliferation and tumor growth and metastasis in vivo by activating RAC1 and CDC42." (PMID 33406731, 2021). "BET bromodomain BRD4 and RAC1 oncogenes are considered important therapeutic targets for cancer and play key roles in tumorigenesis, survival and metastasis." (PMID 34803511, 2021). "It is noteworthy that the PAKs are downstream effectors of small GTPases Rac1 and Cdc42 and are overexpressed in a wide variety of cancers." (PMID 34138895, 2021). "Specific isoforms of CD44, ENAH actin regulator (ENAH), Kruppel-like factor 6 (KLF6), recepteur d’Origine nantais (RON) tyrosine kinase, and Rac family small GTPase 1 (RAC1) can promote cancer cell invasion and migration." (PMID 34771719, 2021). "Results showed that the primary cancer tissue sample of the patient harbored an average of less than two copies of the RAC1 gene, and the resected mediastinal metastasis with resistance and growth on dabrafenib had four copies on average." (PMID 34638434, 2021). "Based on experimental and clinical evidence, Rac1 and Cdc42 have been investigated as potential targets for development of cancer therapeutics." (PMID 33413202, 2021). "The requirement of RAC1 for transformation was first described in the 1990s8, where RAC1 was shown to be overexpressed and its activity increased in many human cancers." (PMID 33397922, 2021). "It is believed that RASAL2 can promote cancer progression by activating the oncoprotein RAC1, a RAS-related small GTPase." (PMID 34966481, 2021). "Upregulation of Rac1 activity has been frequently observed in human cancer and Rac1 inhibitor, such as NSC23766 that we used in this study, is being actively pursued as anticancer therapeutic." (PMID 34325694, 2021). "Previous reports have linked ARHGAP22 activity to cell movement and morphology as well as to actin dynamics in cancer, through its RAC1 regulating activity." (PMID 34455539, 2021). "Inhibition of RAC1 was previously reported to suppress cancer cell growth, invasion and tumor genesis 19 and was hence identified as a promising therapeutic target in different types of cancers 20-22." (PMID 34803511, 2021). "RAC1 can be shuttled from the cytoplasm to the nucleus and abnormal localization, particularly in the nucleus, has been detected in cancer cells." (PMID 34827551, 2021). "Previous studies of the function of KAI1 mostly focused on activation of T cells and inhibition of metastasis and migration through suppression of Rac1/RhoA activity in the cancer cells." (PMID 34530889, 2021).
cancer (continued). "Although other Rho family members are also involved in cancer-related angiogenesis, RAC1 has been proven to be essential in this process, since its activation controls endothelial cell morphogenesis and motility to form a lumen." (PMID 34827551, 2021). "We discovered that cortactin phosphorylated at Y-470 recruits the signaling factor Vav2 to activate the small Rho GTPase Rac1, and finally, a cancer cell motility phenotype." (PMID 34439396, 2021). "Our data showed that in controlling collective cancer polarization, the Golgi apparatus pathways predominate over the Rac1/Cdc42 signaling pathways." (PMID 33499191, 2021). "Hypoxia stimulates angiogenesis and Rac1 signaling has been reported to promote angiogenesis and Rac1 expression correlated with blood vessel invasion in a meta-analysis of multiple cancer studies." (PMID 33413202, 2021). "BVES, as a novel regulator of the Rac1 and Cdc42 signaling cascades, controls cell shape and movement in multiple cancers, including pancreatic cancer." (PMID 33731794, 2021). "Amplification of RAC1 (Ras-related C3 botulinum toxin substrate 1) has been shown to promote cancer metastasis, invasion, migration, epithelial to mesenchymal transition (EMT), angiogenesis, cell cycle progression and drug resistance." (PMID 34803511, 2021). "The ability of cancer cells to migrate to other cells and invade other tissues requires actin cytoskeleton reorganization, which is controlled by the duo of ras-related C3 botulinum toxin substrate 1 (Rac1) and p21 protein-activated kinase 1 (PAK1)." (PMID 34164422, 2021). "We further found that Pals1 prevents cancer cell metastasis by controlling Rac1-dependent cell migration through inhibition of Arf6, which is independent of the canonical binding partners of Pals1." (PMID 33941200, 2021). "The qPCR results showed that KDM6A did not affect the DOCK5 and DOCK8 levels in T24 cells, indicating that KDM6A regulates Rac1 activity in a cancer type-dependent manner." (PMID 34006303, 2021). "To date, overexpression of RAC1 has been observed in breast cancer, while its mutations have been identified in prostate, testicular, melanoma, and NSCLC cancers." (PMID 34771549, 2021). "RAC1 signaling pathway is hyperactivated in human cancers and promotes tumor initiation, progression, and metastatic dissemination." (PMID 34827551, 2021). "Increased expression of RAC1 has been documented in several human cancers and has been correlated with poor prognosis and decreased survival in cancer patients." (PMID 34803511, 2021). "RAC1 is a member of the RHO family of small guanosine triphosphatases that plays an important role in cancer migration, invasion, angiogenesis and metastasis." (PMID 34827551, 2021). "Considering the reliance of K-Ras on Rac1 in cancer development, different Rac-GEFs have been considered as K-Ras effectors, potentially via a PI3K-dependent mechanism." (PMID 34071831, 2021). "As an important goal of cancer prevention and treatment, the relationship between Rac1 and tumorigenesis, proliferation, metastasis, and development of drug resistance has gradually become clear." (PMID 34079763, 2021). "NOX1 can be activated by the small GTPase Ras-related C3 botulinum toxin substrate 1 (RAC1), a Rho GTPase family protein involved in the regulation of migration with a recognized role in cancer metastasis." (PMID 34943045, 2021). "The RAC1 nucleocytoplasmic shuttling was suggested to play a role in cell migration, the nuclear localization of RAC1 promoting potentially the amoeboid mode of motility in cancer cells." (PMID 34368842, 2021). "LncRNA NR2F2-AS1 mediated the up-regulation of Rac1 expression can increase the cancer stemness of clear cell renal cell carcinoma (ccRCC) cells." (PMID 34079763, 2021). "RAC1 was originally identified as an oncogene promoting cancer cell survival and metastasis and essential for transformation by mutant KRAS." (PMID 33603169, 2021).